RNU6-795P (RNA, U6 small nuclear 795, pseudogene)
Gene: Small nuclear RNA gene on chromosome 10 (38,043,873 to 38,043,975, reverse strand). Ensembl gene ENSG00000252132.
Homologues: Orthologues: chimpanzee U6 (99% identical), macaque U6 (91% identical), guinea pig U6 (71% identical), mouse Gm23535 (64% identical), rat LOC120096464 (55% identical). Paralogues in human: RNU6-1170P (92% identical), RNU6-218P (81% identical), RNU6-1209P (80% identical), RNU6-560P (80% identical), RNU6-711P (80% identical), RNU6-774P (79% identical), RNU6-1025P (78% identical), RNU6-1094P (78% identical), RNU6-1340P (78% identical), RNU6-315P (78% identical), RNU6-422P (78% identical), RNU6-727P (78% identical), and 1285 more.